NPRL3 (NPR3 like, GATOR1 complex subunit)
Description:
As a component of the GATOR1 complex functions as an inhibitor of the amino acid-sensing branch of the mTORC1 pathway. In response to amino acid depletion, the GATOR1 complex has GTPase activating protein (GAP) activity and strongly increases GTP hydrolysis by RagA/RRAGA (or RagB/RRAGB) within heterodimeric Rag complexes, thereby turning them into their inactive GDP-bound form, releasing mTORC1 from lysosomal surface and inhibiting mTORC1 signaling. In the presence of abundant amino acids, the GATOR1 complex is negatively regulated by GATOR2, the other GATOR subcomplex, in this amino acid-sensing branch of the TORC1 pathway.
Synonyms: C16orf35; CGTHBA; MARE; RMD11; NPR3; HS-40; FFEVF3
Tractability: Small molecule: a structure with a bound ligand is known. PROTAC: ubiquitination databases record sites on it.
Gene: Protein-coding gene on chromosome 16 (83,205 to 138,716, reverse strand). Ensembl gene ENSG00000103148.
Subcellular location: Lysosome membrane
Subcellular location (Human Protein Atlas): Cytosol
Pathways (Reactome):
Cellular responses to stimuli: Amino acids regulate mTORC1
Gene Ontology:
Molecular function: protein binding
Biological process: cellular response to amino acid starvation; negative regulation of TORC1 signaling; positive regulation of autophagy; negative regulation of TOR signaling
Cellular component: GATOR1 complex; lysosomal membrane
Genetic constraint (gnomAD): Loss-of-function variants: 19 observed, 42.73 expected, observed/expected ratio (o/e) 0.44, 90% interval 0.31 to 0.65. The upper end of that interval is the gene's LOEUF score, 0.65, which puts it in group 2 of 6, group 1 being the genes least tolerant of losing a copy. Missense variants: 665 observed, 693.42 expected, observed/expected ratio (o/e) 0.96, 90% interval 0.9 to 1.02. Synonymous variants: 323 observed, 292.22 expected, observed/expected ratio (o/e) 1.11, 90% interval 1.01 to 1.21.
Gene-disease validity (ClinGen):
ClinGen rates the evidence that NPRL3 causes each of these diseases.
focal epilepsy (autosomal dominant): Definitive. A seizure caused by a localized disorder.
Homologues: Orthologues: macaque NPRL3 (99% identical), dog NPRL3 (97% identical), mouse Nprl3 (96% identical), rat Nprl3 (96% identical), guinea pig NPRL3 (96% identical), chimpanzee NPRL3 (95% identical), rabbit NPRL3 (94% identical), pig NPRL3 (92% identical), tropical clawed frog nprl3 (83% identical), zebrafish nprl3 (78% identical), Drosophila melanogaster Nprl3 (38% identical), Caenorhabditis elegans nprl-3 (20% identical).
Diseases named in the same sentence as NPRL3 in open-access papers:
NPRL3 is named in the same sentence as 47 diseases in open-access papers, as found by Europe PMC text mining. Sharing a sentence is not in itself a finding about the gene and the disease. The quoted sentences say what the papers report.
epilepsy (23 papers, 2019 to 2026). A brain disorder characterized by episodes of abnormally increased neuronal discharge resulting in transient episodes of sensory or motor neurological dysfunction, or psychic dysfunction. "Pathogenic variants in the nitrogen permease regulator-like 3 (NPRL3) gene and other regulators of the mTOR pathway have been linked to diverse epilepsy phenotypes, including SHE." (PMID 41635699, 2026). "DEPDC5 and NPRL3 were two of the most common monogenic causes of epilepsy across 14 NGS studies in adults with epilepsy, together accounting for 7% of all genetic diagnoses made." (PMID 40381056, 2025). "A systematic literature review revealed that 60% of patients with GATOR1 complex gene variants, including NPRL3, achieved seizure freedom following epilepsy surgery." (PMID 39062615, 2024). "Affected individuals displayed markedly heterogeneous epilepsy phenotypes, despite sharing the common truncating founder NPRL3 variant (c.349delG, p.Glu117Lysfs)." (PMID 39062615, 2024). "Among the diverse clinical phenotypes associated with loss‐of‐function variants in GATOR1 genes, NPRL3‐related SUDEP (sudden unexpected death in epilepsy) is of particular interest for pathophysiological reasons and prognostic implications." (PMID 37491868, 2023). "Although a growing interest has recently emerged about the role of mTORopathies in epilepsy, only 35 NPRL3 pathogenic and likely pathogenic variants have been reported in the literature so far." (PMID 37491868, 2023). "The main type of epilepsy due to NPRL3 gene mutations was focal epilepsy, although epilepsy with tonic–clonic seizures (two cases) and neonatal seizures (one case) was also observed." (PMID 36937533, 2023). "The phenotypic spectrum associated with the NPRL3 gene ranges from severe drug-resistant epilepsy associated with developmental impairment to mild epilepsy and infrequent seizures." (PMID 35888005, 2022). "We reviewed the literature and this study, and found that twenty-two of the 25 NPRL3 variants associated with epilepsy were LoF, 15/25 patients were affected with focal epilepsy, and 12/17 with normal brain MRI." (PMID 36685832, 2022). "By analyzing the NPRL3-mTOR signaling pathway in family members in vivo, we confirmed the epilepsy was associated with decreased NPRL3 protein expression levels and increased mTOR pathway activity." (PMID 34868250, 2021). "To date, around 80 different NPRL3 mutations were found to associate with sporadic and familial general epilepsy as well." (PMID 34868250, 2021). "Nprl3 is a component of the gap activity towards rags 1 complex and regulates mTOR complex 1 signaling; it is associated with the pathogenesis of epilepsy and cancer." (PMID 33686256, 2021). "We assembled a cohort of 73 previously unreported probands with rare variants in DEPDC5, NPRL2, and NPRL3 through international networking with diagnostic epilepsy centers." (PMID 30093711, 2019). "In the 11 patients with epilepsy, all NPRL3 gene variants were heterozygous." (PMID 36937533, 2023). "In this study, we reported 11 cases with NPRL3 gene mutations who presented with different kinds of childhood epilepsy, 8 of whom were new reports, which expanded the clinical and genetic spectrum of NPRL3-related epilepsy." (PMID 36937533, 2023). "In fact, loss-of-function mutations in GATOR1 genes such as DEPDC5, NPRL2, and NPRL3) have been frequently associated with malformations of cortical development leading to focal, drug-resistant epilepsy with fair risks of sudden unexpected death in epilepsy (SUDEP)." (PMID 36639812, 2023). "Mutations in STRADA, SYNJ1, CACNA1A and NPRL3 have also been reported with severe epilepsy-related disease, but the association has not been reported for heterozygous variants in isolated forms of epilepsy." (PMID 36539902, 2022).
epilepsy (continued). "We found 12/25 NPRL3 variants currently reported to exhibit incomplete epilepsy penetrance." (PMID 36685832, 2022). "However, we cannot obtain frozen brain tissue samples from the patients in this study, which prevented us from identifying somatic variants in NPRL3 and other epilepsy-related genes." (PMID 36685832, 2022). "However, our results suggest that the NPRL3 gene mutations cannot be excluded in MRI-normal epilepsy patients." (PMID 34868250, 2021). "Our findings expand the genotypic and phenotypic spectrum of the NPRL3-associated epilepsy and reveal the mechanisms of mTOR pathway signaling and GATOR1 pathogenesis in focal epilepsies, providing exciting potential for future diagnostic and therapeutic interventions." (PMID 34868250, 2021). "Nprl2 and Nprl3 mutation are less frequent (6% and 9%, respectively), which might be partially related with the fact that their involvement in epilepsies and brain malformations has been tested in a low number of people." (PMID 34685669, 2021). "Similarly, an individual with an α-globin regulatory region deletion may be at risk of developing epilepsy, due to NPRL3 disruption." (PMID 39062615, 2024). "Furthermore, ISs are the new phenotypes of NPRL3-related epilepsy, while the variants c.275G>A, c.745G>A, and c.1270C>T may be the most common NPRL3 gene mutations." (PMID 36937533, 2023). "Additionally, it seems that NPRL3 mutation‐related epilepsies might have a worst postsurgical outcome (cases 3 and 4 vs. cases 1, 2, 5, and 6)." (PMID 37574648, 2023). "Moreover, the underlying molecular mechanism suggests that mTOR inhibitors, such as rapamycin, may be promising drugs for NPRL3-related epilepsy, due to the abnormal activation of the mTOR signaling pathway caused by NPRL3 gene variation." (PMID 36937533, 2023). "It is thought that the hyperactivation of mTOR pathway, as seen in other disorders such as sclerosis tuberous, PTEN, and GATOR1 complex deficiency (including DEPDC, NPRL2, and NPRL3 deficiencies), may cause epilepsy through the alteration of normal neural networks." (PMID 36003298, 2022). "This deletion encompassed the entire NPRL3 gene, which overlaps the regulatory region of the α-globin gene cluster, giving him the dual diagnosis of NPRL3-related epilepsy and α-thalassemia trait." (PMID 39062615, 2024). "The success of epilepsy surgery often depends on the precise localization of the epileptogenic zone and the presence of FCD, which is frequently associated with NPRL3 mutations." (PMID 39062615, 2024). "A heterozygous full gene deletion of the NPRL3 gene was detected on a multigene next-generation sequencing epilepsy panel, establishing the diagnosis of NPRL3-related epilepsy (NRE)." (PMID 39062615, 2024). "For example, a case report of a neonate with NPRL3-related epilepsy reported 3.5 months of seizure control that allowed the patient to grow seizure-free until epilepsy surgery." (PMID 38612542, 2024). "In this study, we reported 11 Chinese patients with NPRL3-related epilepsy, 8 of whom had not previously been reported, and found ISs as a new phenotype of NPRL3-related epilepsy, expanding the clinical and molecular genetic spectrum of NPRL3-related epilepsy." (PMID 36937533, 2023). "NPRL3‐related epilepsy is more and more emerging as a potentially distinctive entity within the spectrum of GATOR1‐related epileptic disorders." (PMID 37491868, 2023). "Among the remaining patients with neuroimaging abnormalities, FCD was the common presentation of NPRL3-related epilepsy (62.5%), which was consistent with the previous studies." (PMID 36937533, 2023). "Such a favorable surgery outcome, already described in GATORopathies (DEPDC5‐, NPRL2‐, and NPRL3‐related epilepsy), stands in favor of the presurgical sequencing of GATOR1 genes in subjects with either non‐lesional or FCD‐like imaging patterns." (PMID 37491868, 2023).
epilepsy (continued). "EEG results showed that the initial discharge site was changeable, half from the frontal lobe, which was consistent with the clinical presentations that SHE and FLE were the most phenotype in NPRL3-related epilepsy." (PMID 36937533, 2023). "NPRL3 is an important component of the GATOR1 complex, and its mutations can promote the activity of the mTOR signaling pathway, thereby causing epilepsy." (PMID 36937533, 2023). "A total of 11 Chinese children with NPRL3-related epilepsy were identified through whole-exome sequencing (WES)." (PMID 36937533, 2023). "A total of 12 children with definite epileptogenic foci were surgically treated, and 9 were seizure-free post-surgery; thus, surgery represents a highly effective treatment in 75% of the patients with NPRL3-related epilepsy." (PMID 36937533, 2023). "As one of the assembly factors of the GATOR1 protein complex in the mechanism of rapamycin pathway, NPRL3 plays an important role in the pathogenesis of epilepsy." (PMID 36937533, 2023). "SHE and FLE were the most common clinical presentations, and ISs are a new phenotype of NPRL3-related epilepsy." (PMID 36937533, 2023). "All previously reported cases with NPRL3-related epilepsy were collected and reviewed through PubMed search." (PMID 36937533, 2023). "Our study expanded the clinical and genetic spectrum of NPRL3-related epilepsy and provided important information for the precise treatment of patients." (PMID 36937533, 2023). "Among the 11 children, eight have not been reported, and two of them presented infantile spasms (ISs) as a new phenotype of NPRL3-related epilepsy." (PMID 36937533, 2023). "Because the pathogenesis of NPRL3 gene variation was haploinsufficiency, patients with LOF variants have a severe clinical phenotype of epilepsy." (PMID 36937533, 2023). "For 73% of patients with NPRL3-related epilepsy, monotherapy of sodium channel blockers was effective." (PMID 36937533, 2023). "A case report of a neonate with NPRL3-related epilepsy reported 3.5 months of seizure control that allowed the patient to grow seizure-free until epilepsy surgery." (PMID 35250833, 2022). "In striking contrast to other GATOR1 components, and especially to its paralogue NPRL2, NPRL3 seems to be less important for epilepsy and cancer." (PMID 34685669, 2021). "Our results further emphasize the role of aberrant regulation of mTOR signaling in NPRL3 mutation–related seizures and NPRL3 LOF in the genesis of epilepsy." (PMID 34868250, 2021). "NPRL3 In the previous studies, NPRL3 gene mutations are reported to be the likely cause for malformation of cortical development (MCDs) and MCD-related epilepsy." (PMID 34868250, 2021). "Because somatic variants in GATOR1-encoding genes (>400 in DEPDC5, >80 in NPRL2, and >100 in NPRL3 in the COSMIC database) have been mentioned in various cancers, we examined cancer occurrence in epilepsy probands carrying germline GATOR1 variants." (PMID 30093711, 2019). "While the primary focus of NPRL3 research has been on its role in epilepsy, it is recognized that if this gene and surrounding regions are deleted, α-thalassemia phenotypes can co-occur, given its genomic location near the α-globin gene cluster on chromosome 16p13.3." (PMID 39062615, 2024). "Combined with our study, a total of 88 patients with NPRL3-related epilepsy were found, of which 57 were boys and 30 were girls, respectively, while the gender of one case was unknown." (PMID 36937533, 2023). "Indeed, we found two cases of IS as a new phenotype of NPRL3-related epilepsy in our study, which complement the clinical phenotype of NPRL3-related epilepsy." (PMID 36937533, 2023). "However, given our limited cases, future studies need more patients with NPRL3-related epilepsy to confirm this." (PMID 36937533, 2023). "The genotypes and clinical phenotypes of 11 children with NPRL3-related epilepsy." (PMID 36937533, 2023). "Up to June 2022, 77 patients with NPRL3-related epilepsy had been reported previously." (PMID 36937533, 2023).
epilepsy (continued). "A recent paper confirmed that epilepsy surgery may be effective in some children with GATOR1 complex gene variants, including NPRL3 and seizure outcomes may be compromised by extensive epileptogenic zones." (PMID 37491868, 2023). "Genetic and clinical features of subjects with NPRL3‐related epilepsy." (PMID 37491868, 2023). "Up to June 2022, a total of 77 patients with NPRL3-related epilepsy had been reported in PubMed." (PMID 36937533, 2023). "NPRL3-related epilepsy has high clinical and genetic heterogeneity." (PMID 36937533, 2023). "Thus, a PET scan is needed in the future to reveal the subtle metabolic or biochemical function changes in the brain of patients with NPRL3-related epilepsy." (PMID 36937533, 2023). "All six patients with deletion of the NPRL3 gene had drug-resistant epilepsy, suggesting that the phenotype of the deletion variant may be the most severe variant of LOF in NPRL3 gene variations." (PMID 36937533, 2023). "Among 76 cases with the age of onset, NPRL3-related epilepsy could occur from infancy to adulthood, suggesting more attention should be given to NPRL3 gene variations of epilepsy across all ages." (PMID 36937533, 2023). "Our results also showed that 60.8% of patients with NPRL3-related epilepsy had drug-resistant epilepsy, consistent with the previous studies, which may be due to the high occurrence of FCD among patients with neuroimaging abnormalities." (PMID 36937533, 2023). "It was interesting to find that individuals with heterozygous NPRL3 mutations in the parents’ generations did not exhibit epilepsy phenotypes, and the calculated overall penetration did not exceed 50%." (PMID 36685832, 2022). "GATOR1-related epilepsies caused by DEPDC5, NPRL2, and NPRL3 variations exhibit various phenotypes consisting of sleep-related focal hypermotor seizures, infantile spasms, and other focal epilepsies, including frontal, temporal, occipital, parietal, centrotemporal epilepsies." (PMID 34376795, 2022). "In the present study, the mothers were both revealed to carry a heterozygous NPRL3 variant without any epilepsy phenotypes in these two families, which further confirms the incomplete penetrance of NPRL3 in FFEVF3." (PMID 36685832, 2022). "Other disorders of cellular proliferation—including Sturge-Weber syndrome caused by mutations in GNAQ, NPRL3-related cortical malformations, and PIK3CA-related overgrowth syndromes—also present with epilepsy that seems responsive to “rapalogs” like sirolimus and everolimus." (PMID 35250833, 2022). "The NPRL3 pedigree exhibited incomplete epilepsy penetrance." (PMID 36685832, 2022). "The more recent discovery of epilepsy-causative NPRL2 and NPRL3 variants and the greater length of the DEPDC5 transcript (5551 bp) compared with NPRL2 (1700 bp) and NPRL3 (2881 bp) have been offered as explanations for the increased frequency of DEPDC5-associated epilepsies." (PMID 34632383, 2021). "Pathogenic variants in NPRL3, mostly loss-of-function or truncating mutations, like nonsense and frameshift variants, cause a spectrum of epilepsy phenotypes collectively termed NPRL3-related epilepsy (NRE)." (PMID 39062615, 2024). "Therefore, these pieces of evidence indicated that epilepsy surgery might be a suitable option for patients of NPRL3-related epilepsy with neuroimaging abnormalities, especially with FCD." (PMID 36937533, 2023). "Sodium channel blockers may be the preferred treatment for NPRL3-related epilepsy." (PMID 36937533, 2023). "Additionally, two cases had ongoing seizures after surgery or ASMs but were treated effectively by receiving KD, suggesting that KD may be a potential option for patients of NPRL3-related epilepsy unresponsive to surgery or ASMs." (PMID 36937533, 2023). "The current treatment of epilepsy with NPRL3 gene variants is lacking in specificity." (PMID 36937533, 2023).
epilepsy (continued). "Malformations of cortical developments are common in NPRL3 patients, especially FCD 2a, and their prevalence is comparable to DEPDC5‐related epilepsy." (PMID 37491868, 2023). "NPRL3‐related epilepsy is slightly more common among females and a similar gender disparity was reported in the prevalence of DEPDC5 and NPRL2‐related epilepsy." (PMID 37491868, 2023). "Epilepsy caused by NPRL3 may not necessarily manifest structural abnormalities in the brain." (PMID 36685832, 2022). "However, the correlation between genotype and clinical phenotype in patients with NPRL3-related epilepsy has not been clarified." (PMID 36937533, 2023). "However, the details on whether the new phenotypes and genotypes of the NPRL3 gene do exist and the information on the correlation between genotype and clinical phenotype in patients with NPRL3-related epilepsy have not been clarified." (PMID 36937533, 2023). "It was worth noting that most NPRL3-related epilepsy exhibited no intracranial structural damage (70%), suggesting that the epileptogenic mechanisms of the NPRL3 gene may be associated with a relatively wide range of neurofunctional abnormalities and the formation of the epileptogenic network." (PMID 36937533, 2023).